HTT (huntingtin)
Diseases named in the same sentence as HTT in open-access papers (continued):
Sharing a sentence is not in itself a finding about the gene and the disease.
Huntington disease (continued). "Huntington’s disease (HD) arises from the abnormal expansion of CAG repeats in the huntingtin gene (HTT), resulting in the production of the mutant huntingtin protein (mHTT) with a polyglutamine stretch in its N-terminus." (PMID 38612657, 2024). "Huntington's disease (HD) is a degenerative brain ailment caused by an increase in CAG (cytosine–adenine–guanine) repeats in the IT15 gene, also known as the huntingtin (HTT) gene." (PMID 39153206, 2024). "Huntington’s disease (HD) is a hereditary degenerative disorder characterized by the expansion of CAG triplet repeats (>36) in the first exon of the HTT gene located on chromosome 4q." (PMID 39684197, 2024). "We visualized the distribution of UBL3 in postmortem brain tissue, specifically within the neurons of the striatum in Huntington’s disease (HD) patients, and identified its interaction with polyQ-expanded huntingtin fragments." (PMID 39449505, 2024). "We have used these, in combination with immunohistochemistry, to map the appearance and accumulation of aggregated huntingtin throughout the CNS of zQ175 mice, a model of Huntington’s disease frequently chosen for preclinical studies." (PMID 36756307, 2023). "Expansion of CAG triplets in the huntingtin gene (HTT) on chromosome 4 is responsible for Huntington’s disease (HD)." (PMID 37761821, 2023). "Huntington’s disease (HD) is caused by an expanded CAG repeat in the huntingtin gene, yielding a Huntingtin protein with an expanded polyglutamine tract." (PMID 36754966, 2023). "In Parkinson’s disease, so-called Lewy bodies (LB) are formed, mainly containing primarily alpha-synuclein, while in Huntington’s disease, protein aggregates rich in polyglutamine residues are formed (called huntingtin)." (PMID 36984809, 2023). "Huntington’s disease (OMM: 143100) is an autosomal dominant neurodegenerative disorder resulting primarily from a toxic gain of function of the HTT protein." (PMID 38116140, 2023). "In Huntington’s disease, the PIP3 binding protein linked with FYVE protein (Alfy/Wdfy3) is the adaptor protein required for the degradation of mutant HTT." (PMID 37627261, 2023). "Huntington’s disease (HD) is an incurable, autosomal dominant, neurodegenerative disease caused by an expanded CAG repeat in the huntingtin gene." (PMID 37761400, 2023). "Measuring Huntingtin (HTT) protein in peripheral cells represents an essential step in biomarker discovery for Huntington’s Disease (HD), however to date, investigations into the salivary expression of HTT has been lacking." (PMID 36658243, 2023). "It has been described as both a potential modulator of protein aggregation and neuroprotective factor in Huntington’s disease by inhibiting the aggregation of the mutant huntingtin." (PMID 36899835, 2023). "A previous study from our group has demonstrated that glycogen accumulation can partially rescue the toxicity induced by mutant Huntingtin (Htt) protein in a cellular model of Huntington's disease (HD)." (PMID 37681238, 2023). "Huntington’s disease (HD) is a progressive inherited neurological disease characterized by the degeneration of basal ganglia and the accumulation of mutant huntingtin (mHtt) aggregates in specific brain areas." (PMID 36807563, 2023). "Huntington’s disease (HD) is a monogenic neurodegenerative disorder characterized by a CAG repeat expansion in the Huntingtin (HTT) gene." (PMID 36908787, 2023). "A randomised placebo-controlled double-blind study in patients with Huntington’s disease demonstrated a dose-dependent decrease in the concentration of mutant HTT in the cerebrospinal fluid (CSF) following intrathecal administration of HTTRx." (PMID 37240368, 2023). "For example, reduced Wnt signaling has been shown to protect against mutant Huntingtin toxicity in Drosophila and prolong the lifespan of flies with Huntington’s disease." (PMID 36983079, 2023).
Huntington disease (continued). "HTT (huntingtin) is known to be involved in Huntington’s disease signalling, but also required for normal development, including vesicle transport, protein trafficking, and transcriptional regulation." (PMID 36860523, 2023). "Huntington’s disease (HD) is an inherited neurodegenerative disorder driven by the presence of long CAG sequence repeats in the Huntingtin protein, making it prone to aggregation." (PMID 37123415, 2023). "UKH-1114 alleviates mechanical hypersensitivity following nerve injury, and it reduces neuronal toxicity induced by mutant huntingtin protein in a model of Huntington's disease." (PMID 38117854, 2023). "When this is not kept under control, proteins can form pathogenic aggregates that lead to neurodegeneration (e.g., α-synuclein in Parkinson’s disease; amyloid β and tau in Alzheimer’s disease; huntingtin in Huntington’s disease)." (PMID 38115822, 2023). "In Huntington's disease (HD) the primary site of dysfunction is the corticostriatal synapse, where mutant huntingtin (htt) modifies the striatal excitatory synaptic activity by modulating N-methyl-d-aspartate receptor (NMDAR) signaling." (PMID 37464831, 2023). "For example, tominersen, a 2′-MOE ASO to target huntingtin for Huntington’s disease (ClinicalTrials.gov Identifier: NCT02519036; NCT03761849) showed no serious adverse effects in phase 2 trials, but phase 3 trials were stopped due to lack of efficacy." (PMID 38192302, 2023). "Enhancing glycogen synthesis in the brains of flies with Huntington's disease decreased mutant Huntingtin aggregation and reduced oxidative stress by activating auto-lysosomal functions." (PMID 37681238, 2023). "The expansion of trinucleotide repeats in the HTT gene is central to the pathogenesis of Huntington’s disease." (PMID 38132886, 2023). "Our own work on cellular models of Huntington’s disease found reduced huntingtin expression and slowed aggregation kinetics of disease-linked huntingtin proteins in cells expressing tRNASerAAA." (PMID 36833445, 2023). "One such disorder, Huntington’s disease, is caused by an increased number of glutamine-encoding trinucleotide repeats CAG in the first exon of the huntingtin (HTT) gene." (PMID 37680383, 2023). "A recent study in Huntington’s disease patients showed that reactive astrocytes activated via the JAK2/STAT3 pathway were able to reduce the toxic huntingtin protein aggregation in neurons." (PMID 37219933, 2023). "In cellular and mouse models of Huntington’s disease, DnaJB2 and DnaJB6 reduce mutant Huntingtin aggregation and delay the onset of Huntington’s disease, whereas other JDPs do not significantly suppress aggregation." (PMID 36581212, 2023). "Huntington’s Disease (HD) is caused by a CAG repeat expansion, leading to accumulation and impaired clearance of mutant huntingtin protein." (PMID 37168844, 2023). "Huntingtin-lowering approaches that target huntingtin expression are a major focus for therapeutic intervention for Huntington’s disease." (PMID 36756307, 2023). "Huntington’s disease (HD) is a dominant late-onset genetic disorder that is primarily characterized by an abnormal expansion of CAG repeats within the N terminus of the huntingtin (Htt) protein." (PMID 37476290, 2023). "LBs exhibit a striking morphological similarity to the inclusions found in Huntington's disease, another debilitating neurodegenerative disease, which contain the polyglutamine-rich protein huntingtin as the main component." (PMID 38149872, 2023). "Huntington’s disease (HD) is an autosomal dominant progressive brain disorder, caused by a pathological expansion of a CAG repeat that encodes the huntingtin gene." (PMID 36983567, 2023). "In mouse models of Huntington's disease, expression of Abhd11os was reduced or dysregulated and its overexpression had neuroprotective effects in mice against mutant huntingtin-induced toxicity." (PMID 37089489, 2023).
Huntington disease (continued). "Huntington's disease (HD) is a neurodegenerative disease resulting from an expansion of the polyglutamine (polyQ) domain within the huntingtin protein (htt)." (PMID 37052951, 2023). "Huntington's disease (HD) is characterized by the intracellular accumulation of mutant huntingtin (mHTT) that can be soluble and aggregated in the central nervous system and causes neuronal damage and death." (PMID 37688357, 2023). "Huntington's disease (HD) is a progressive neurodegenerative disorder induced by the expansion of a CAG repeat in the huntingtin gene on chromosome 4, which leads to mutant huntingtin protein misfolding in neurons and microglial cells." (PMID 37377861, 2023). "Huntington’s disease (HD) is a hereditary, monogenic disease caused by a CAG expansion in the N-terminus of the huntingtin (HTT) gene." (PMID 36547263, 2023). "Background and objectives: Huntington’s disease (HD) is characterized by motor, cognitive and psychiatric manifestations and caused by an expansion of CAG repeats over 35 triplets on the huntingtin (HTT) gene." (PMID 37761821, 2023). "Huntington’s disease (HD) is a progressive, neurodegenerative disease caused by a CAG triplet expansion in huntingtin." (PMID 36914640, 2023). "Huntington disease (HD; OMIM 143 100) is an autosomal dominant neurodegenerative disorder caused by a pathogenic expansion of the CAG trinucleotide in the huntingtin (HTT) gene." (PMID 36130218, 2023). "Huntington’s disease (HD, OMIM: #143100) is a fatal, late-onset neurodegenerative disorder caused by a dominant gain-of-function mutation in the Huntingtin (HTT, HGNC: 4851) gene." (PMID 37569316, 2023). "Huntington’s disease (HD) is a fatal, dominantly inherited neurodegenerative disorder caused by CAG trinucleotide expansion in exon 1 of the huntingtin (HTT) gene." (PMID 36510111, 2023). "Huntington’s disease (HD) is a dominantly inherited neurodegenerative disorder resulting from a CAG expansion in the huntingtin (HTT) gene, which leads to the production and accumulation of mutant huntingtin (mHTT)." (PMID 36651994, 2023). "Huntington’s disease (HD), one of the neurodegenerative disorders, is characterized by the expansion of CAG repeats that encode polyglutamine in the HTT gene." (PMID 36833410, 2023). "In Huntington’s disease (HD), huntingtin protein (HTT) regulates Rab11-dependent transport, which is involved in maintaining dendritic spine size." (PMID 38203282, 2023). "Huntington's disease (HD) is an autosomal dominant, late-onset, and fatal neurodegenerative disorder, which is caused by an abnormal CAG repeat in the huntingtin gene." (PMID 35910843, 2022). "Participants between 6 and 18 years old were recruited from families affected by Huntington's disease and tested for the huntingtin gene expansion." (PMID 35604958, 2022). "Many neurodegenerative disorders display protein aggregation as a hallmark, Huntingtin and TDP-43 aggregates being characteristic of Huntington disease and amyotrophic lateral sclerosis, respectively." (PMID 35409310, 2022). "Huntington’s disease (HD) is an inherited and late-onset neurodegenerative disorder caused by a CAG-repeat expansion within the Huntingtin (HTT)." (PMID 36395338, 2022). "Translated polyglutamine expansions in the huntingtin protein, if higher than 35 repeats, lead to the aggregation of huntingtin (HTT) protein and the development of Huntington’s disease." (PMID 35265969, 2022). "Anti-Huntington (HTT) siRNAs effectively reduce the expression of HTT gene and slow the disease’s progression in mice with Huntington’s disease (HD)." (PMID 36311034, 2022). "Huntington’s disease (HD) is just such an example of a fatal neurological disorder, where mutated genes (CAG trinucleotide expansions in the Huntingtin gene) have widespread expression, leading to the production of mutant Huntingtin (mHTT) protein." (PMID 35626712, 2022).
Huntington disease (continued). "Huntington's disease (HD) is a fatal, neurodegenerative disorder caused by a CAG repeat expansion in the huntingtin (HTT) gene on chromosome 4 (OMIM 143100)." (PMID 35604958, 2022). "Huntington’s disease is a genetic, neurodegenerative disorder caused by an abnormal coronary artery angiography (CAG) repeat expansion in the Huntingtin (HTT)gene." (PMID 36519153, 2022). "Our findings identify mutant HTT/HTT1a mRNA clustering as an early, robust molecular signature of Huntington’s disease, providing in vivo evidence that Huntington’s disease is a repeat expansion disease with mRNA involvement." (PMID 36458209, 2022). "Chemically modified siRNAs distinguish between mutant and normal huntingtin based on a single nucleotide difference and lower mutant huntingtin specifically in patient derived cells and in a mouse model of Huntington’s disease." (PMID 36192390, 2022). "The best known is the huntingtin protein (Htt), responsible for the neurodegenerative disorder Huntington’s disease." (PMID 36298715, 2022). "Huntington’s disease is an autosomal, dominant, neurodegenerative disease caused by a CAG repeat mutation in the Huntingtin gene (HTT)." (PMID 35169703, 2022). "Post‐mortem tissues from Huntington's disease (HD) patients show increased hypertrophy in astrocytes which contain mutant huntingtin (mHtt) aggregates." (PMID 35535566, 2022). "The list of such neurodegenerative disorders includes Huntington’s disease: this is a fatal, inherited neurodegenerative disease caused by CAG triplet expansions within exon 1 of the huntingtin gene (HTT)." (PMID 35626712, 2022). "Huntingtin-lowering strategies are a major focus of therapeutic development for Huntington’s disease." (PMID 35793238, 2022). "Deletion of SUMO1 in a Huntington’s disease mouse model or inhibition of sumoylation by Ginkgolic acid in human Huntington’s disease patient-derived fibroblasts strongly enhanced autophagy, promoting the clearance of toxic Huntingtin protein inclusions." (PMID 35269436, 2022). "In Huntington disease, an expansion of the polyglutamine (polyQ) tract in the N terminus of the HTT protein leads to protein aggregation." (PMID 36371383, 2022). "Huntington disease is a neuro degenerative disease formed due to huntingtin protein structural deformation through the expansion of polyglutamine." (PMID 35164374, 2022). "Huntington’s disease (HD) is a fatal autosomal dominant neurodegenerative disease characterized by CAG repeat expansion in exon 1 of Huntingtin (HTT)." (PMID 35213386, 2022). "The ortholog of Huntington’s disease protein Huntingtin (Htt) regulates myosin II phosphorylation through phosphatase PP2A, affecting chemotaxis and cytokinesis." (PMID 36231128, 2022). "For Huntington’s disease (HD), also a trinucleotide repeat disorder, multiple AONs designed to reduce the production of the huntingtin protein have been developed with promising results from early clinical trials." (PMID 35067193, 2022). "We found that glycation modulates the pathogenicity of both aSyn and huntingtin, central players in PD and in Huntington’s disease, respectively." (PMID 35468899, 2022). "The conserved huntingtin gene (HTT) is known for its role in the neurodegenerative disorder Huntington disease (HD)." (PMID 35810172, 2022). "There is an extensive range of genetic rodent models of Huntington’s disease, including rapidly progressing transgenic mutant huntingtin fragment models and slower progressing full length transgenic and ‘knock-in’ models." (PMID 35262656, 2022). "MEG3 has previously been shown to promote the aggregation of the mutant huntingtin gene in the neuroblastoma cell model of Huntington’s disease." (PMID 36552881, 2022). "Huntington’s disease is an autosomal dominant progressive nervous system disorder brought on by glutamine expansion in the huntingtin protein (HTT), resulting in muscle wasting, motor and cognitive impairments, psychiatric disorders, and neurodegeneration." (PMID 36618820, 2022).
Huntington disease (continued). "A CAG repeat-targeting artificial miRNA lowers the mutant huntingtin level in the YAC128 model of Huntington disease (HD)." (PMID 35664700, 2022). "Huntington’s disease (HD) is characterised by the trinucleotide expansion of a CAG repeat found in exon 1 of the Huntingtin (HTT) gene." (PMID 36497196, 2022). "In order to establish a method to directly identify the components of NIIs, we first analyzed the huntingtin inclusion-rich fraction obtained from the brains of Huntington disease model mice." (PMID 35246273, 2022). "Huntington disease is characterized by progressive neurodegeneration, especially of the striatum, and the presence of polyglutamine huntingtin (HTT) inclusions." (PMID 35440014, 2022). "Various genes enriched in modern humans are disease-relevant genes like CHD8 and CPEB4 in autism spectrum, HTT in Huntington’s disease, FOXP2 in language impairment." (PMID 36550402, 2022). "Huntington’s disease (HD) is a rare genetic neurodegenerative disorder resultant of excessive extension of CAG repeats within the huntingtin gene." (PMID 35529444, 2022). "Huntington’s disease is typically characterized by chorea and psychiatric symptoms, in which expansion of repeat sequences (poly-glutamine or poly-Q) in the huntingtin protein (HTT) drives its aggregation." (PMID 35517053, 2022). "For example, huntingtin, the Huntington disease protein, was introduced as a new hub of the network in PICKLE 2.6 due to a targeted PPI experiment." (PMID 35053288, 2022). "It is also noteworthy that huntingtin, the protein involved in Huntington’s disease, also has mono-amino acid repeats of both polyQ and polyP." (PMID 36388907, 2022). "Sphk1 codes for sphingosine kinase 1, which is reported to promote protective autophagy of aggregated huntingtin proteins in Huntington’s disease." (PMID 36428550, 2022). "Huntingtin is thought to be a key protein of the devastating neurodegenerative disorder Huntington’s disease (HD), which is critical for microtubule-mediated transport, vesicle function, autophagy, and transcription." (PMID 36474209, 2022). "Crmp1 is also found within mutant Huntingtin inclusions, and suppresses neurotoxicity in Huntington’s disease models." (PMID 34933920, 2022). "Huntington’s Disease (HD) is an autosomal, dominantly inherited neurodegenerative disorder caused by an expansion of the CAG repeat in the huntingtin (HTT) gene." (PMID 35455705, 2022). "A global Gpr52 knockout, as well as GPR52 antagonist (E7) treatment has been reported to reduce Huntington’s disease-related symptoms and mutant huntingtin (mHTT) levels in mouse primary striatal neurons." (PMID 36761164, 2022). "In Huntington’s disease (HD), quantifying the amount of huntingtin protein (HTT) in patient cerebrospinal fluid (CSF) has served as a pharmacodynamic readout for HTT-lowering therapeutic approaches and is a potential disease progression biomarker." (PMID 35938256, 2022). "Over-activation of SNCA exacerbates Huntingtin protein (HTT)-induced toxicity in Huntington’s disease, while its deacetylation by sirtuins affects its aggregation propensity." (PMID 36523604, 2022). "The intriguing properties shown by the MS3 aptamer open new valuable perspectives in the therapeutic approaches for Huntington’s disease based on specifically targeting mutant huntingtin." (PMID 35563194, 2022). "This corresponds to a symptomatic stage of Huntington’s disease with an apparent presence of mutant Huntingtin aggregates and significant changes in a number of neurological and behavioural tests." (PMID 35628260, 2022). "Recent failures of the first clinical trials involving huntingtin-lowering approaches to Huntington’s disease emphasize the need to keep all therapeutic options on the table, including relatively new concepts such as enviromimetics and exercise mimetics." (PMID 36519152, 2022).